SOST (sclerostin)
Diseases named in the same sentence as SOST in open-access papers (continued):
Sharing a sentence is not in itself a finding about the gene and the disease.
sclerosteosis (continued). "Sclerostin is expressed by the SOST gene and was originally identified in patients with sclerosteosis and van Buchem’s disease." (PMID 35705746, 2022). "However, not all sclerosteosis cases are caused by variants in SOST." (PMID 35052419, 2021). "Sclerostin defects are responsible for the metabolic bone disorders known as SOST-related sclerosing bone dysplasia, which include three different entities: Sclerosteosis (MIM 269500), Van Buchem Disease (VBD; MIM 239100), and the SOST-related craniodiaphyseal dysplasia (CDD; MIM 122860)." (PMID 40943101, 2025). "Van Buchem disease is less severe than sclerosteosis and the difference in severity lies in the fact that, in van Buchem patients, there is some residual expression of the SOST gene, whereas, in patients with sclerosteosis, there is none." (PMID 35052478, 2022). "Whereas sclerosteosis patients have no detectable protein in circulation, heterozygous carriers of SOST mutations have serum sclerostin levels approximately half that of control subjects and bone mineral density (BMD) values higher than age-matched controls." (PMID 33776907, 2021). "The difference in severity lies in that in patients with Van Buchem, wild-type sclerostin is low, whereas in patients with sclerosteosis it is absent." (PMID 33419004, 2021). "In contrast to sclerosteosis patients, in which functional sclerostin is completely absent, van Buchem disease patients have a reduced sclerostin expression compared to healthy controls." (PMID 32366042, 2020). "Clinical data from sclerosteosis and Van Buchem patients who lack sclerostin do not report an increased incidence of cardiovascular events in these patients which suggests that targeting sclerostin does not cause cardiovascular disease." (PMID 32328030, 2020). "Mice lacking sclerostin reflect some symptoms of sclerosteosis, but this is the first report of the effect on the facial skeleton." (PMID 31729194, 2020). "Consistent with this restricted expression of sclerostin, patients with sclerosteosis have no renal or cardiovascular abnormalities." (PMID 26892377, 2016). "In healthy adults, sclerostin is expressed by osteocytes, but not in patients with sclerosteosis and van Buchem disease." (PMID 26041376, 2015). "Rare monogenic disorders such as osteogenesis imperfecta, juvenile Paget disease, and sclerosteosis have illuminated critical bone regulatory pathways—indeed, the therapeutic target for romosozumab was identified through study of sclerosteosis patients lacking functional sclerostin." (PMID 41517353, 2025). "However, there have been no reports of increased cardiovascular events in sclerosteosis, van Buchem disease, or sclerostin knockout mice, and there is a lack of scientific evidence suggesting that romosozumab strongly leads to cardiovascular events." (PMID 31698687, 2019). "As expected, sclerostin was not expressed in bone biopsies from patients with sclerosteosis." (PMID 26892377, 2016). "As in patients with sclerosteosis and van Buchem disease, serum calcium and phosphate concentrations in SOST-KO mice were not different from those of their wild-type littermates while serum osteocalcin values were increased with no changes in serum TRAP5b values." (PMID 27016922, 2016). "Sclerostin, the protein of the Sost gene, is an osteocyte-specific inhibitor of bone formation, which when absent results in the sclerosing bone disorder sclerosteosis." (PMID 25850409, 2015). "Therefore, the absence of sclerostin in the bones of patients with sclerosteosis may result in hyperactivation of Wnt signaling, leading to bone overgrowth." (PMID 35208525, 2022). "In addition, two mutations in low-density lipoprotein receptor-related protein 4 (LRP4) have been found in sclerosteosis patients, independent of the sclerostin genotype, demonstrating that LRP4 interacts with sclerostin or mediates its function." (PMID 35563144, 2022).
diabetes (93 papers, 2013 to 2026). "In our study, serum sclerostin level was significantly higher in patients with diabetes than in controls, especially in the DN group, which indicates an association of serum sclerostin level with glucose metabolism." (PMID 40353858, 2025). "Further studies are warranted to fully elucidate the mechanisms underlying the changes in Sost/sclerostin expression in diabetes." (PMID 39171525, 2024). "In the multivariable backward stepwise linear regression analysis adjusted for age, sex, body mass index, and diabetes mellitus, sclerostin was an independent risk factor of PH." (PMID 38341544, 2024). "The model included variables that were found to be associated with sclerostin based on prior bivariate analysis, including age, diabetes duration, eGFR, diastolic blood pressure, LDL-c, calcium, and periostin." (PMID 37919715, 2023). "The low-density lipoprotein receptor-related protein 5 (LRP5) and its inhibitor sclerostin, are key components of bone metabolism and potential contributors to type 2 diabetes mellitus susceptibility." (PMID 36947076, 2023). "Sclerostin levels were substantially increased in patients with diabetes mellitus, associated with inhibition of the Wnt/β-catenin pathway and increased bone fragility." (PMID 37025406, 2023). "For example, irisin was positively correlated with the osteocalcin level in healthy children but negatively associated with the sclerostin level in adults with pre-diabetes." (PMID 36926035, 2023). "It was also reported that increased blood sclerostin level is significantly associated with insulin resistance in skeletal muscle, liver, and adipose tissue in patients with diabetes." (PMID 35216490, 2022). "In terms of further limitations, the lack of detailed information about use of medications prevented us from examining their contribution to observed associations between sclerostin and risk factors such as diabetes mellitus." (PMID 34738659, 2022). "After adjustments for potential confounders, high serum sclerostin was independently associated with the low muscle mass index and with presence of diabetes." (PMID 35565832, 2022). "A previous study also suggested that sclerostin levels were positively associated with the years of having diabetes and glycated haemoglobin levels, and inversely associated with bone turnover markers." (PMID 34690653, 2021). "Previous studies found that sclerostin levels increase with age, menopause, insulin resistance and type 2 diabetes mellitus, while a debated association with obesity exists." (PMID 34679612, 2021). "This study determined the prevalence of sarcopenia in patients undergoing hemodialysis and evaluated the association in these patients of diabetes and concentrations of serum sclerostin." (PMID 32095286, 2020). "The aim of this study is to determine the prevalence in patients undergoing hemodialysis of sarcopenia and its association with diabetes and with sclerostin levels." (PMID 32095286, 2020). "Serum sclerostin levels presented a negative association with muscle mass index, while a positive association was observed between the presence of diabetes and sclerostin levels." (PMID 32095286, 2020). "Based on the Spearman correlation analysis, the serum sclerostin levels were positively associated with diabetes (p = 0.004), but negatively associated with dialysis duration (p = 0.036), diastolic BP (p = 0.002), and iPTH (p = 0.037) in the HD group." (PMID 32216514, 2020). "Sclerostin levels were associated positively with age, male sex, weight, height, diabetes, BMD, and serum uric acid levels and negatively with total Kt/V for urea, osteocalcin levels, and intact PTH levels." (PMID 31315601, 2019). "After adjustment for age, gender, and diabetes, sclerostin was still independently associated with CIMT (OR = 1.161, 95%CI: 1.046–1.288, p = 0.005)." (PMID 30314461, 2018).
diabetes (continued). "Our results showed that IFX, a TNF-α antagonist, decreased alveolar bone loss and expression levels of osteocytic RANKL and sclerostin in STZ-induced diabetes rats with periodontitis." (PMID 29240821, 2017). "We found that serum sclerostin was significantly associated with duration of diabetes or HbA1C in the univariate analysis." (PMID 25053944, 2014). "In the present study, serum sclerostin was significantly associated with duration of diabetes after adjusting for age, sex, and eGFR (β = 0.192, P < 0.001, data not shown), which disappeared after adjusting further confounders." (PMID 25053944, 2014). "Conversely, another meta-analysis analyzed 5069 participants from two large cohorts (LURIC and ALSPAC mothers), and presented that high sclerostin levels were associated with a higher risk of diabetes, which was deemed as a risk factor for cardiovascular disease." (PMID 40149867, 2025). "In addition to the classic BTMs, other biochemical markers such as advanced glycation end products (AGEs), adipokines, cytokines, and sclerostin have been suggested to be associated with bone fragility in diabetes." (PMID 37155585, 2023). "Another study showed that diabetes caused osteocytes to alter over time and upregulate the sclerostin gene, that might be mediated by local glucose concentrations and could have a significant effect on the deterioration of bone quality." (PMID 37215218, 2023). "Recent studies show that sclerostin, a Wnt signaling inhibitor, is associated with diabetes." (PMID 36004027, 2022). "Additionally, these sclerostin gene variants were also found to be associated with arterial hypertension (OR = 1.12) and diabetes mellitus (OR = 1.15)." (PMID 34822428, 2021). "Additionally, serum sclerostin levels were positively associated with age (p < 0.001), gender (p = 0.031), diabetes (p = 0.004), and history of CVEs (p = 0.022), but negatively associated with diastolic BP (p = 0.045) in the PD group." (PMID 32216514, 2020). "The association of sclerostin with chronic inflammation has been suggested because several inflammatory cytokines stimulate sclerostin expression in osteocytes under pathological conditions, including obesity, diabetes, and CVD." (PMID 32544571, 2020). "However, they adjusted for only age to investigate the association between duration of diabetes and sclerostin." (PMID 25053944, 2014). "Additionally, and in line with these findings, lower levels of sclerostin appeared to be causally associated with higher levels of triglycerides in UK Biobank, and a higher risk of type 2 diabetes mellitus in both the meta-analysis of GWAS and our analysis of UK Biobank." (PMID 39537602, 2024). "Higher sclerostin levels were associated with higher risk of diabetes mellitus (DM) (odds ratio [OR] = 1.25; 95% confidence interval [CI] 1.12, 1.37), risk of elevated fasting glucose (OR 1.15; CI 1.04, 1.26), and triglyceride levels (β 0.03; CI 0.00, 0.06)." (PMID 34738659, 2022). "Hence, the use of therapeutic agents which could target BMP-2 and sclerostin might prove beneficial in improving diabetes-linked osteoporosis." (PMID 35928902, 2022). "Thus, sclerostin seemed to have a predictive value for fracture risk in patients with diabetes." (PMID 36120431, 2022). "Therefore, intermittent PTH administration may improve bone formation and attenuate diabetes-aggravated bone loss by decreasing sclerostin expression in osteocytes of type 1 diabetic rats with periodontitis." (PMID 29544500, 2018). "Thus, the independent variables included in the multiple logistic regression model were, apart from sclerostin, those variables biologically linked to mortality risk (age, presence and duration of diabetes, sex, prevalent CVD, pIMT, tobacco use, hypertension and eGFR)." (PMID 29928063, 2018). "Sclerostin promotes adipogenesis and, given that adipose tissue has endocrine functions affecting energy metabolism, the endocrine role of bone is critical in diabetes research." (PMID 39941397, 2025).
diabetes (continued). "The meta-analysis results highlight advanced age, prolonged dialysis duration, concomitant diabetes, hypertension, hyperparathyroidism, and elevated levels of CRP, hs-CRP, and SOST as key risk factors for CAC in ESRD patients." (PMID 40314886, 2025). "Overall, the effects of sclerostin on diabetes warrants further validation in RCTs applying sclerostin inhibitors, which will be discussed later." (PMID 40149867, 2025). "This study highlights the potential of targeting sclerostin’s local effects within the LCS as a therapeutic strategy to prevent bone deterioration in diabetes." (PMID 40352664, 2025). "A cross-sectional study found that sclerostin levels gradually increased from healthy controls to prediabetes and diabetes patients." (PMID 40149867, 2025). "Increased sclerostin levels have been reported in patients with type 2 diabetes mellitus (T2DM), and serum sclerostin concentration has been shown to be negatively correlated with skeletal muscle mass." (PMID 40943733, 2025). "Serum sclerostin levels are elevated in diabetes, yet its role in bone fragility is not fully understood." (PMID 40352664, 2025). "Two, characterizing serum and plasma markers (resorption CTX, formation P1NP, sclerostin, insulin, insulin-like growth factor 1, IL-6, TNFα, etc.)would identify potential metabolic pathways by which diet and diabetes lower the fracture resistance of bone." (PMID 39012489, 2024). "The effect of type 2 diabetes mellitus (T2DM) on sclerostin and CTRP3 levels in postmenopausal women is rarely investigated." (PMID 39237913, 2024). "The regulation of Sost/sclerostin in the context of diabetes is not completely understood and likely results from the combined effects of metabolic and hormonal changes induced by the disease in vivo." (PMID 39171525, 2024). "In the hyperglycaemic LepR−/− animals, sclerostin levels were substantially higher than in the euglycaemic LepR+/+ animals at both time points, which is in accordance with clinical findings in type 2 diabetes mellitus patients." (PMID 37730735, 2023). "The independent variables included in the model were age, sex, hypertension, dyslipidaemia, eGFR, sedentarism, tobacco use and years of diabetes duration, in addition to serum sclerostin level." (PMID 37919715, 2023). "In recent years, a meta-analysis involving 66 studies showed that CTX, OC, and P1NP levels in patients with diabetes were lower than those in controls, while the levels of sclerostin and OPG were higher than those in controls." (PMID 36120431, 2022). "The study of Catalano proved that, in the group of patients with type 1 diabetes mellitus, there is a difference in serum sclerostin concentrations between women and men." (PMID 36675692, 2022). "In this sense, sclerostin levels are related to insulin resistance, are higher in diabetics and in patients affected by metabolic syndrome, and positively correlate with body fat, although (as with BMD or BMC) some discrepancy exists regarding this matter." (PMID 35807755, 2022). "Fourth, we noticed the impact of age, postmenopausal women, and history of diabetes on the serum levels of sclerostin." (PMID 35546224, 2022). "Diabetes is one of the responsible factors in regulating sclerostin concentration and is proven by a previous in-vitro study that reports that hyperglycemia results in sclerostin overexpression in murine cell lines." (PMID 35928902, 2022). "It was concluded that serum sclerostin is directly related to diabetes and inversely related to muscle mass in hemodialysis patients." (PMID 35565832, 2022). "There was a gradual increase in sclerostin levels from healthy [242.12(158.44)] to prediabetes [256.06(299.65)] and diabetes [465.76 (735.71)] with a significant (<0.001) difference from healthy reference." (PMID 36004027, 2022). "It was reported that sclerostin concentration is elevated in diabetes patients independently of eGFR." (PMID 36675692, 2022).
diabetes (continued). "This explains why the sclerostin level in participants with diabetes in this study was higher than that in healthy controls." (PMID 34690653, 2021). "Studies also emphasized the potential role of sclerostin in relation to adiposity and type 2 diabetes mellitus." (PMID 34679612, 2021). "A previous study also reported that sclerostin levels increased in type 2 diabetic patients, independent of age and sex, and were correlated with the duration of diabetes, glycated haemoglobin levels, and bone mass density." (PMID 34690653, 2021). "This study assesses the serum levels of insulin-like growth factor-1 (IGF-1) and sclerostin as markers of decreased bone formation in premenopausal women with type 2 diabetes mellitus." (PMID 34690653, 2021). "Subjects with diabetes had significantly higher phosphate, albumin, C-reactive protein, brain natriuretic peptide and sclerostin levels (61.1 vs 39.3 pmol/L, P = 0.035), compared to those without diabetes." (PMID 34644326, 2021). "In multivariate linear regression models, the serum sclerostin levels correlated positively with diabetes (p = 0.035), but correlated negatively with diastolic BP (p = 0.012) in the HD group." (PMID 32216514, 2020). "We found higher serum sclerostin concentrations in hemodialysis patients with diabetes which were inversely related to muscle mass." (PMID 32095286, 2020). "Serum sclerostin levels were significantly higher in individuals with low muscle mass index (94.9 ± 40.7; p < 0.001) and in those individuals with diabetes (97.2 ± 46.6; p < 0.003)." (PMID 32095286, 2020). "Infliximab, which is a TNF-α antagonist, inhibits sclerostin and RANKL expression in osteocytes and attenuates alveolar bone loss in periodontitis rats with diabetes." (PMID 32708317, 2020). "Sclerostin levels increase with aging and persist higher in some diseases (e.g., diabetes, chronic kidney disease) that are known to precipitate atherosclerosis and enhance cardiovascular risk." (PMID 32640551, 2020). "In patients with type 1 diabetes mellitus, high serum DKK1 and SOST were closely associated with both glycemic control and biochemical markers of bone turnover." (PMID 31197079, 2019). "Altogether, our findings suggest that diabetes induces longstanding changes in osteocytes, leading to upregulation of sclerostin." (PMID 31757981, 2019). "There are a few studies suggesting that hyperglycaemia facilitates or induces this differentiation, since circulating levels of sclerostin seem to be increased in atherosclerotic disease in Type 2 diabetes mellitus." (PMID 30496210, 2018). "Our previous work showed severe alveolar bone loss and inhibition of alveolar bone formation with elevated sclerostin expression on day 20 in rats with STZ-induced diabetes and periodontitis." (PMID 30413166, 2018). "In conclusion, we have shown that circulating sclerostin level negatively correlated with eGFR in diabetes patients with wide range of renal function." (PMID 25053944, 2014). "Sclerostin serum concentrations depend on genetic aspects, as well as age, sex, adiposity, kidney function and presence of diabetes mellitus." (PMID 25280749, 2014). "Duration of diabetes significantly and positively was correlated with serum sclerostin in the entire cohort (r = 0.381, P < 0.001)." (PMID 25053944, 2014). "They reported that serum sclerostin was correlated with duration of diabetes and glycated hemoglobin in patients with type 2 diabetes." (PMID 25053944, 2014). "Recently, the inverse correlation between serum levels of sclerostin and osoteocalcin in diabetes was reported despite animal model." (PMID 23785354, 2013). "Regarding AVC (Agatston score) the univariate analysis resulted in inclusion of age, male sex, diabetes and serum sclerostin to the multivariable analysis." (PMID 24112318, 2013). "Similarly, sclerostin, secreted by osteocytes, is highly secreted in patients with diabetes and leads to compromised glucose tolerance and insulin sensitivity." (PMID 40149867, 2025).